CDH15 (cadherin 15)
Description:
Cadherins are calcium-dependent cell adhesion proteins. They preferentially interact with themselves in a homophilic manner in connecting cells; cadherins may thus contribute to the sorting of heterogeneous cell types. M-cadherin is part of the myogenic program and may provide a trigger for terminal muscle differentiation.
Synonyms: CDH14; CDH3; CDHM; MCAD; MRD3
Tractability: Antibody: its Gene Ontology location is reachable by antibodies, with high confidence; UniProt places it where antibodies can reach, with medium confidence; UniProt predicts a signal peptide or a membrane-spanning region; the Human Protein Atlas places it where antibodies can reach. PROTAC: ubiquitination databases record sites on it.
Gene: Protein-coding gene on chromosome 16 (89,171,748 to 89,195,492, forward strand). Ensembl gene ENSG00000129910.
Subcellular location: Cell membrane
Subcellular location (Human Protein Atlas): Golgi apparatus; Plasma membrane
Pathways (Reactome):
Cell-Cell communication: Adherens junctions interactions
Developmental Biology: Myogenesis
Gene Ontology:
Molecular function: protein binding; beta-catenin binding; cadherin binding; calcium ion binding
Biological process: adherens junction organization; calcium-dependent cell-cell adhesion; cell adhesion; cell migration; cell morphogenesis; cell-cell adhesion mediated by cadherin; cell-cell junction assembly; cell-cell adhesion; homophilic cell-cell adhesion
Cellular component: extracellular exosome; plasma membrane; adherens junction; catenin complex; caveola; membrane; neuromuscular junction
Genetic constraint (gnomAD): Loss-of-function variants: 73 observed, 62.91 expected, observed/expected ratio (o/e) 1.16, 90% interval 0.96 to 1.41. The synonymous counts are far from expectation, so gnomAD's model fits this gene poorly and the ratio says little. Missense variants: 1,343 observed, 1,101.1 expected, observed/expected ratio (o/e) 1.22, 90% interval 1.16 to 1.28. Synonymous variants: 624 observed, 490.03 expected, observed/expected ratio (o/e) 1.27, 90% interval 1.19 to 1.36.
Gene-disease validity (ClinGen):
ClinGen rates the evidence that CDH15 causes each of these diseases.
intellectual disability (autosomal dominant): Disputed.
Homologues: Orthologues: chimpanzee CDH15 (96% identical), macaque CDH15 (86% identical), mouse Cdh15 (83% identical), rat Cdh15 (82% identical), pig CDH15 (82% identical), dog CDH15 (82% identical), tropical clawed frog cdh15 (55% identical), zebrafish cdh15 (44% identical). Paralogues in human: CDH4 (41% identical), CDH2 (40% identical), CDH1 (37% identical), CDH3 (36% identical), CDH12 (31% identical), CDH7 (30% identical), CDH6 (30% identical), CDH11 (29% identical), CDH18 (29% identical), CDH22 (29% identical), CDH9 (29% identical), CDH8 (29% identical), and 21 more.
Diseases named in the same sentence as CDH15 in open-access papers:
CDH15 is named in the same sentence as 34 diseases in open-access papers, as found by Europe PMC text mining. Sharing a sentence is not in itself a finding about the gene and the disease. The quoted sentences say what the papers report.
Intellectual disability (5 papers, 2012 to 2025). "Summary of reports of CDH15 variants in cases of intellectual disability published to date." (PMID 41368060, 2025). "Of clinical interest, the human CDH15 gene has been associated with intellectual disability." (PMID 22902559, 2012). "CDH15 (Cadherin 15): Mental retardation, autosomal dominant 3 (intellectual disability and impairments in adaptive behavior)." (PMID 31031802, 2019).
epilepsy (3 papers, 2017 to 2025). A brain disorder characterized by episodes of abnormally increased neuronal discharge resulting in transient episodes of sensory or motor neurological dysfunction, or psychic dysfunction. "We analyzed OLINK proteomics data from a large epilepsy cohort in which we have previously found four differentially expressed proteins (CDH15, PAEP, LTBP3, PHOSPHO1)." (PMID 40591616, 2025). "In addition, we observed some downregulated genes (such as MPZ, GJB1, CDH15, KCNQ3, and PLP1) in K-NSC cells, and abnormal expression of these genes has been reported to cause cognitive impairment, epilepsy, spasticity, and myelin abnormalities, which are similar to the disease symptoms of GLD." (PMID 37076788, 2023).
schizophrenia (3 papers, 2017 to 2025). A major psychotic disorder characterized by abnormalities in the perception or expression of reality. "CDH15 variant was among the variants found in the older brother with moderate ID and ASD in addition to schizophrenia." (PMID 41368060, 2025).
autism (2 papers, 2014 to 2018). Persistent deficits in social interaction and communication and interaction as well as a markedly restricted repertoire of activity and interest as well as repetitive patterns of behavior. "Cadherin 15 (CDH15) gene has been found in a sporadic patient with autism." (PMID 24756565, 2014). "Notably, these included transcripts for adhesion proteins such as CDH13, CDH9, CDH15 and SLITRKs, all strongly linked to ASD, presynaptic molecules such as SYNIII and SV2C, associated with non-syndromic autism and SCZ, and post-synaptic transcripts such as DLGAP2 and GRIN2D, linked to SCZ." (PMID 30185603, 2018).
CHARGE syndrome (2 papers, 2017 to 2025). CHARGE syndrome is a multiple congenital anomaly syndrome characterized by the variable combination of multiple anomalies, mainly Coloboma; Choanal atresia/stenosis; Cranial nerve dysfunction; Characteristic ear anomalies (known as the major 4 C's). "Remarkably, some patients with a CDH15 deletion share specific clinical traits with CHARGE syndrome, associated with heterozygous CDH7 variants." (PMID 28422132, 2017).
rhabdomyosarcoma (2 papers, 2020 to 2025). A rare aggressive malignant mesenchymal neoplasm arising from skeletal muscle. "Corroborating the increase in the expression of CDH15 along with MYOD1 in our model of rhabdomyosarcoma CSCs, MYOD1 knockdown has been demonstrated to significantly downregulate CDH15 expression." (PMID 31941033, 2020). "In a model of RAS-driven rhabdomyosarcoma tumorigenesis, expression of KRAS under the CDH15 promoter resulted in less differentiated and more aggressive tumors." (PMID 31941033, 2020). "This approach enabled us to identify several novel and promising rhabdomyosarcoma CSC-specific targets, e.g., ALDH6A1, SOX4, PAX3, CDH15, downregulated MIR145, or phosphorylated RYK, which warrant validation in subsequent mechanistic studies." (PMID 31941033, 2020). "Since we have not yet investigated other types of sarcomas, such as rhabdomyosarcoma, it is worthwhile to identify more tumors expressing CDH15." (PMID 40688506, 2025).
autosomal dominant intellectual disability type 3 (1 paper, 2020). "Heterozygous variants in CDH15 have been reported in families with autosomal dominant intellectual disability type 3 (MRD3; OMIM #612580)." (PMID 32604767, 2020).
ischemia (1 paper, 2021). A hypoperfusion of the BLOOD through an organ or tissue caused by a PATHOLOGIC CONSTRICTION or obstruction of its BLOOD VESSELS, or an absence of BLOOD CIRCULATION. "Under nonischemic conditions, pericytes expressed Cdh19, Cdh6, Cdh10, Cdh4, Cdh13, and Cdh5; after ischemia, the cadherin genes that were predominantly expressed were Cdh15, Cdh11, Cdh3, and Cdh2." (PMID 33726849, 2021).
melanoma (1 paper, 2018). A malignant, usually aggressive tumor composed of atypical, neoplastic melanocytes. "The observed post-treatment effect inducing over-expressions in both CDH3 and CDH15 is therefore neutralizing the loss of cell-cell dependent adhesion and influencing melanoma development and progression." (PMID 30485296, 2018).
osteosarcoma (1 paper, 2025). A usually aggressive malignant bone-forming mesenchymal neoplasm, predominantly affecting adolescents and young adults. "Since Ca15Mab-1 exhibits a superior reactivity among Ca15Mabs, we next investigated the reactivity of Ca15Mab-1 against endogenous CDH15-expressing cell lines, human osteosarcoma Saos-2 and mouse myoblast C2C12." (PMID 40688506, 2025). "Furthermore, Ca15Mab-1 recognizes endogenous CDH15-expressing human osteosarcoma (Saos-2) and mouse myoblast (C2C12) cell lines." (PMID 40688506, 2025).
sarcoidosis (1 paper, 2025). Sarcoidosis is a multisystemic disorder of unknown cause characterized by the formation of immune granulomas in involved organs. "Through rigorous sensitivity analyses, we ultimately identified three proteins as priority candidates with significant druggable potential: CDH15 for ILD excluding IPF, ADAM15 for both IPF and ILD, and LTBR for sarcoidosis." (PMID 39824903, 2025).
soft tissue sarcoma (1 paper, 2020). A malignant neoplasm arising from muscle tissue, adipose tissue, blood vessels, fibrous tissue, or other supportive tissues excluding the bones. "This is in agreement with our survival analysis on soft-tissue sarcomas demonstrating that upregulated expression of ALDH6A1 but not ALDH1A1 or ALDH3A1 significantly correlates with poor survival when combined with other genes identified in our model, i.e., CDH15, MYOD1, SOX4, ARMCX1, and RYK." (PMID 31941033, 2020).
teratoma (1 paper, 2020). A non-seminomatous germ cell tumor characterized by the presence of various tissues which correspond to the different germinal layers (endoderm, mesoderm, and ectoderm). "The levels of Myf5 and Cdh15 mRNA and proteins were lower in Pax7−/− teratomas, what indicates abnormal formation or maintenance of satellite cell population." (PMID 32552916, 2020).
cancer (4 papers, 2014 to 2025). A tumor composed of atypical neoplastic, often pleomorphic cells that invade other tissues. "Yet, the downregulation of the type II collagen gene (COL2A1) in PC3SFRP2, which is involved in cancer stemness in various cancer types, and the upregulation of CDH15 (Cadherin 15) in PC3SFRP2, which mediates intracellular adhesion, are promising predictors of the role of SFRP2 in cancer metastasis." (PMID 36552843, 2022).
tumor (4 papers, 2012 to 2025). "Conversely, we observed a significant downregulation of tumor-suppressive transcriptional regulators such as CPEB1, CDH15, GFPT2, and PLA2G2A." (PMID 40950184, 2025). "Concordantly hypermethylated CpGs were associated with genes involved in Cadherin, Wnt and Notch signaling pathways, many of which have been previously reported as frequently methylated in a variety of neoplasms, such as APC2, SFRP2, CDH13, CDH15 and PCDH10." (PMID 22737091, 2012).
neurodevelopmental disorder (3 papers, 2022 to 2025). A behavioral and cognitive disorder with onset during the developmental period that involves impaired or aberrant development of intellectual, motor, or social functions. "Variants in ASD-associated genes (CHD8, FOXP1, and SHANK1) and genes linked to other neurodevelopmental disorders (CDH15, GATAD2B, and SHROOM4) were also detected." (PMID 40642607, 2025). "Instead, we identified several rare, likely pathogenic variants in seven genes implicated in neurodevelopmental disorders: KLHL17, TDO2, TRRAP, EIF3F, ATP10A, DICER1, and CDH15." (PMID 35743796, 2022).
CDH15 also shares sentences with these, for which no sentence is quoted: sarcoma (2 papers); Alzheimer disease (1); amyotrophic lateral sclerosis (1); autosomal dominant intellectual disability (1); breast tumors (1); Cognitive impairment (1); depression (1); Granuloma (1); infection (1); lung carcinoma (1); mental disorder (1); Mental retardation, autosomal dominant 3 (1); metastatic tumors (1); multiple sclerosis (1); Parkinson disease (1); pulmonary fibrosis (1); tuberculosis (1); X-linked mental retardation syndrome (1).